BCAT1 (branched chain amino acid transaminase 1)
Diseases named in the same sentence as BCAT1 in open-access papers (continued):
Sharing a sentence is not in itself a finding about the gene and the disease.
glioma (continued). "To investigate whether CHIP/BCAT1 axis correlates with the sensitivity of glioma cells to temozolomide, we examined the IC50 values of temozolomide using CCK-8 assay." (PMID 39075053, 2024). "Furthermore, the BCAT1K360R mutant displays prolonged stability, linking ubiquitin modification to heightened BCAT1 expression in glioma." (PMID 39075053, 2024). "Additionally, we show that the CHIP/BCAT1 axis enhances glioma sensitivity to temozolomide by reducing glutathione (GSH) synthesis and increasing oxidative stress." (PMID 39075053, 2024). "To elucidate the regulatory mechanism governing BCAT1 post-translational modification and expression in glioma cells, we conducted a ubiquitin assay to evaluate BCAT1 ubiquitination levels in human malignant glioblastoma multiforme U251 and U87 cells, as well as in human microglial HMC3 cells." (PMID 39075053, 2024). "Importantly, our previous study demonstrated that targeted inhibition of BCAA metabolism and BCAT1 induces apoptosis in glioma both in vitro and in vivo." (PMID 39075053, 2024). "Notably, BCAT1 promotes cell proliferation in aggressive gliomas, and BCAT1 inhibition in combination with α-ketoglutarate triggers metabolic synthetic lethality in glioma cells." (PMID 39075053, 2024). "Furthermore, a positive correlation is observed between low CHIP expression, elevated BCAT1 levels, and unfavorable prognosis among glioma patients." (PMID 39075053, 2024). "Inhibiting glioma BCAT1 expression reduces glutamate release with BCAAs’ accumulation." (PMID 36295820, 2022). "Moreover, in glioma, prostate cancer, and urothelial cancer, it has been demonstrated that the prognosis of tumor patients with upregulated BCAT1 expression was poor." (PMID 34984849, 2022). "High expression of BCAT1 promotes gastric cancer, lung cancer, breast cancer, prostate cancer, glioma, hepatocellular carcinoma, urothelial cancer, melanoma, lymphoma, esophageal squamous cell carcinoma, head and neck squamous cell carcinoma, and nasopharyngeal carcinoma." (PMID 36119495, 2022). "BCAT1 is enriched in IDH1 wild-type gliomas and may relate to apoptosis, hypoxia and angiogenesis processes in tumor progression." (PMID 33493139, 2021). "Furthermore, to evaluate potential biological processes that BCAT1 involves in the progression of glioma, we performed a pilot study where we examined the coexpression pattern of BCAT1 with different functional gene subgroups." (PMID 33493139, 2021). "To further delineate the impact of BCAT1 gene expression on the patients’ treatment response, we conducted an overview of BCAT1 expression together with several genetic alterations which are known to be related with progression of glioma." (PMID 33493139, 2021). "This is the first comprehensive study to characterize BCAT1 expression in all grades of glioma molecularly and clinically and may provide bases for further evaluation of the roles BCAT1 in glioblastoma progression." (PMID 33493139, 2021). "In fact, in contrast to BCAT2 (almost ubiquitously expressed), BCAT1 has limited expression in adult tissues (except for the nervous system and activated T cells), while it is often expressed in many tumors such as gliomas, ovarian cancer, non-small lung carcinoma, and myeloid leukemia." (PMID 34445444, 2021). "Moreover, the association between BCAT1 and IDH1 status was also confirmed, as previously reported, high expression of BCAT1 is observed in IDH1 wild-type gliomas but is also preferentially expressed in non 1p19q co-deleted gliomas." (PMID 33493139, 2021). "Collectively, these data indicate that BCAT1 is enriched in glioma tissues and upregulated in GBMs." (PMID 33493139, 2021). "Moreover, BCAT1 is an independent prognostic factor for glioma patients, high BCAT1 expression is related to unfavorable clinical parameters including older age, IDH wildtype, no 1p/19q codeletion, ATRX wildtype and MGMT unmethylated." (PMID 33493139, 2021).
glioma (continued). "IDH-mutant gliomas convert isocitrate into 2-hydroxyglutarate, which competitively inhibits α-KG-dependent DNA and histone demethylases, contributing to the downregulation of BCAT1/2 function through DNA methylation of its promoter." (PMID 34445444, 2021). "Furthermore, we explored the potential regulatory mechanism of BCAT1 in gliomas by comparing the BCAT1 mRNA expression pattern with selected tumor biological signatures." (PMID 33493139, 2021). "Moreover, BCAT1 is also involved in the glycolytic metabolism and immune suppression of IDH1 wild-type gliomas, suggesting multiple roles that BCAT1 exerts in the malignant transformation of glioblastoma." (PMID 33493139, 2021). "Additionally, BCAT1 correlated with apoptosis, hypoxia and angiogenesis processes in gliomas and high expression of BCAT1 revealed higher glycolysis level and increased immunosuppressive status in tumor progression." (PMID 33493139, 2021). "Furthermore, we took advantage of clinical human glioma samples to detect the protein pattern of BCAT1 and IDH1 R132H in glioma tissues." (PMID 33493139, 2021). "In turn, inhibition of BCAT1 led to a lower amount of glutamate excretion of glioma cells." (PMID 30716120, 2019). "As an important enzyme, BCAT1 was up-regulated in gliomas, breast cancer and myeloid leukaemia." (PMID 29541009, 2018). "ASL and ASS1 protein levels were mostly undetected in high grade gliomas, whereas BCAT1 was high." (PMID 28245795, 2017). "In gliomas carrying the endogenous IDH mutation, BCAT1 is silenced via promoter hypermethylation." (PMID 28074274, 2017). "Our results support the findings of previous studies that demonstrated increased conversion of glutamate to α-KG by GLUD and reduced conversion of α-KG to glutamate by BCAT1 in IDH1MUT glioma, which is in line with promoter methylation of BCAT1 in IDH1MUT glioma." (PMID 28467784, 2017). "Importantly, several previous studies have shown that the expression of BCAT1 is necessary for the progression of IDH1 WT gliomas, which sustain an aggressive growth phenotype, and our data are in line with previous reports." (PMID 27626306, 2016). "Additionally, U87-CHIP cells treated with temozolomide exhibited a higher ratio of apoptotic cells in comparison to wild-type U87 cells and U87-CHIP/BCAT1K360R cells, indicating that CHIP-mediated BCAT1 degradation promoted temozolomide sensitivity in glioma cells." (PMID 39075053, 2024). "Tönjes reported that BCAT1 protein expression was absent in IDH-mutated gliomas." (PMID 37298317, 2023). "Thus, highly expressed BCAT1 indicates a poor prognosis for gliomas with wild-type IDHs." (PMID 36295820, 2022). "In addition, it has been reported that inhibition of BCAT1 in glioma cell lines prevents the proliferation and development of tumor cells by disturbing with tumor energy production and macromolecular synthesis, breakdown and metabolism of BCAAs, and reducing tumor glutamate excretion." (PMID 36119495, 2022). "The results showed that BCAT1 is increasingly expressed in glioma tissues corresponding to increasing tumor grade, and compared to IDH1 wild-type diffuse glioma patients, the patients that had gained IDH1 R132H mutation showed a lower percentage of tumor cells with detectable BCAT1 expression." (PMID 33493139, 2021). "To illuminate the biological features of glioma with different BCAT1 expression, we examined the correlation of BCAT1 expression with angiogenesis, apoptosis and hypoxia marker genes to evaluate the relationship between BCAT1 expression and tumor microenvironment." (PMID 33493139, 2021). "Besides, high BCAT1 expression represents poor survival of IDH1 wild-type gliomas." (PMID 33493139, 2021). "In addition, BCAT1 was reported to promote cell proliferation in gliomas carrying wild-type IDH1." (PMID 27323413, 2016). "In sum, these data suggest that aberrant expression of BCAT1 and CHIP contributes to glioma progression and can serve as prognostic markers for glioma patients." (PMID 39075053, 2024).
glioma (continued). "Branched-chain amino acid transaminase 1 (BCAT1), a key enzyme in branched-chain amino acid (BCAA) catabolism, exhibits elevated expression in gliomas and correlates strongly with poor prognosis." (PMID 39075053, 2024). "The analysis revealed concomitantly high BCAT1 expression and low CHIP expression in patients with advanced glioma grades." (PMID 39075053, 2024). "We also found HIF-1α induced in hypoxia cultured glioma cells, and the expressions of LDHA and BCAT1 were also increased." (PMID 37298317, 2023). "S2 cells are analogous to glioma cells expressing mutant IDH, where the production of 2HG is thought to silence BCAT1 expression." (PMID 37885806, 2023). "A large number of previous research reports have presented that the expression level of BCAT1 plays a crucial role in the occurrence and development of IDH1 wild-type gliomas." (PMID 36119495, 2022). "The function of BCAT1 and BCAT2 have been widely reported in various types of cancers, such as gliomas and chronic myeloid leukaemia." (PMID 35326233, 2022). "We searched the expression level of candidate genes by GEPIA and found that only five genes (F11R, YBX1, BCAT1, IMPAD1, and RP2) were significantly upregulated in gliomas." (PMID 35402226, 2022). "In gliomas, 2HG, which is a competitive inhibitor of multiple α-KG-dependent dioxygenases, produced by mutant-IDH1, has been found to inhibit BCAT1 and BCAT2." (PMID 33367952, 2021). "The results showed that the overall survival (OS) time of glioma patients with higher BCAT1 expression (TCGA, IDH1WT:67.8%; CGGA, IDH1WT:74.5%) is shorter than patients with lower BCAT1 expression (TCGA, IDH1WT:5.9%; CGGA, IDH1WT:14.8%)." (PMID 33493139, 2021). "Branched-chain aminotransferase 1 (BCAT1) generates glutamate during BCAA catabolism and is overexpressed in many cancers including glioma." (PMID 34685601, 2021). "BCAT1 expression was positively correlated with glycolytic enzymes, which are enriched in IDH1 wild-type gliomas and related to poor overall survival of glioma patients." (PMID 33493139, 2021). "In particular, D-2HG can inhibit BCAT1 and BCAT2, inducing glioma cells dependent on glutaminase and more sensitive to oxidative stress compared to IDH wild-type glioma cells." (PMID 33923299, 2021). "Previous studies have shown that the branched-chain aminotransferase 1 and 2 (BCAT1 and BCAT2) enzymes, which catalyze the first step of BCAAs degradation, are overexpressed in gliomas, pancreatic cancer, and non-small-cell lung carcinoma." (PMID 32238881, 2020). "One key function of astrocytes is neurotransmitter homeostasis including rapid removal of glutamate from the synaptic space, and both enhanced xCT and BCAT1 expression and reduced EAAT2 expression occur in gliomas." (PMID 30716120, 2019). "D-2HG also inhibits the branched-chain amino acid transaminase 1 (BCAT1) and 2 (BCAT2), which renders IDH1 mutant glioma cells dependent on glutaminase and increases their sensitivity to oxidative stress." (PMID 31450721, 2019). "Moreover, CHIP expression negatively correlates with BCAT1 expression in glioma tissues, with low CHIP expression correlating with the poor prognosis for glioma patients." (PMID 39075053, 2024). "2-HG could inhibit the activity of both BCAT1 and BCAT2, resulting in impaired synthesis of glutamate and the extensive reliance on glutaminase of gliomas." (PMID 36295820, 2022). "The results showed that BCAT1 is highly expressed in GBM versus lower grade gliomas and could represent the poor survival of IDH1 wild-type gliomas." (PMID 33493139, 2021). "Interestingly, D-2HG also affects BCAT1, possibly due to direct inhibition of enzyme activity or DNA hypermethylation within the main promoter region of BCAT1 in IDH1-mutant gliomas." (PMID 34067762, 2021). "Nonetheless, as a promising target for treatment of primary glioblastoma, comprehensive reports on BCAT1 in gliomas are still lacking." (PMID 33493139, 2021).
glioma (continued). "In glioma with non-mutated isocitrate dehydrogenase (IDH), branched-chain amino acids such as leucine and isoleucine, and their catabolizing enzyme branched-chain amino acid transaminase 1 (BCAT1), are more expressed – in turn, BCAT1 knock-down in glioma cells reduces the viability of glioma cells." (PMID 34926298, 2021). "Moreover, BCAT1 and CHIP expression displayed a negative correlation in glioma tissue microarray samples." (PMID 39075053, 2024).
breast carcinoma (47 papers, 2013 to 2025). "In breast cancer, BCAT1 has been linked to mTOR signaling, enhancing mitochondrial function and cancer cell growth." (PMID 40083932, 2025). "High BCAT1 in breast cancer patients has been linked to poor prognosis." (PMID 41502503, 2025). "Down-regulation of Bcat1 would result in the accumulation of BCAAs in cells the tissues, which is a core mechanism underlying several types of cancer, including leukemia, nonsmall cell lung cancer, pancreatic adenocarcinoma, and breast cancer." (PMID 29802157, 2018). "For example, compared to untreated primary breast cancer, BCAT1 mRNA levels were elevated in tamoxifen-resistant breast cancer samples, and an increased level of BCAT1 expression was associated with an unfavourable prognosis in antioestrogen-resistant breast cancer." (PMID 32571264, 2020). "BCAT1 promotes mitochondrial biogenesis, ATP production, and inhibits mitochondrial ROS in breast cancer cells by regulating the expression of related genes." (PMID 40438606, 2025). "Elevated expression of BCAT1 has been observed in breast cancer, and knocking down BCAT1 can inhibit the growth and proliferative capacity of breast cancer cells." (PMID 40438606, 2025). "In experimental models, BCAT1 overexpression promotes breast cancer cell proliferation and invasiveness, partly by supplying intermediates to the TCA cycle and activating mTOR signaling to enhance mitochondrial biogenesis." (PMID 41502503, 2025). "Changes in BCAA levels in plasma and tissue are accompanied by an elevated expression of BCAT1 in breast cancer." (PMID 40723225, 2025). "In breast cancer, BCAT1 can trigger the mTORC1 pathway, leading to increased mitochondrial biogenesis and ATP synthesis, which provide energy for growth and colony formation of tumor cells." (PMID 40723225, 2025). "Similar findings have been reported in breast cancer, where BCAT1 expression correlates with increased BCAA levels in tumour tissue and serum, and mTORC activity.(L. Zhang & Han, 2017)." (PMID 40839139, 2025). "In a study by Zhang and Han, elevated levels of BCAT1 were found to stimulate proliferation and mTOR activity in breast cancer." (PMID 40066850, 2025). "BCAT1 activates the mTORC1 pathway to play a pro-oncogenic role in breast and endometrial cancers, while BCAT1 inhibits mitochondrial reactive oxygen species (ROS) production in breast cancer cells." (PMID 39324007, 2024). "In breast cancer, knockdown of BCAT1 eliminates BCAA catabolism, which inhibits mTOR-mediated mitochondrial biogenesis and function, repressing cancer proliferation." (PMID 38305803, 2024). "In breast cancer, BCAT1 activated mTORC1 signaling, increased mitochondrial biogenesis, and thereby promoted cell growth." (PMID 37460470, 2023). "In contrast, an investigation revealed that in breast cancer, along with BCAT1, the expression of BCKDHA and BCKDHB was upregulated, thus promoting tumor cell growth." (PMID 37637065, 2023). "Elevated concentrations of BCAAs, both in plasma and tissues, have also been observed in the context of breast cancer, concomitant with increased expression of catabolic enzymes, including branched-chain amino acid transaminase 1 (BCAT1)." (PMID 38089615, 2023). "In contrast, breast cancer displays enhanced BCAA catabolism with higher gene expression of BCAT1, BCKD and other downstream enzymes." (PMID 35409380, 2022). "The overexpression of BCAT1 promotes tumor growth in gynecological cancers, as in ovarian cancer and breast cancer." (PMID 35574395, 2022). "In antiestrogen-resistant breast cancer cells, BCAT1 is the most highly upregulated transcript compared to antiestrogen-sensitive breast cancer cells." (PMID 35011702, 2022). "In HR+ breast cancer cell lines, activation of BCAT1 activity through mTOR signaling has been shown to promote cell growth in vitro by regulating mitochondrial function and biogenesis." (PMID 34638293, 2021).